EPO (erythropoietin)
Diseases named in the same sentence as EPO in open-access papers (continued):
Sharing a sentence is not in itself a finding about the gene and the disease.
Obesity (continued). "On the other hand, renal hypoxemia related to obesity and MASLD causes the kidneys to release erythropoietin, which stimulates erythropoiesis and the production of erythroferrone." (PMID 41226991, 2025). "Some previous studies reported that EPO treatment improved glucose tolerance in high-fat diet-induced obesity and insulin-resistant model animals, suggesting the possibility that EPO is a novel therapeutic agent for insulin resistance." (PMID 40943240, 2025). "In sum, current studies strongly suggest that EPO exerts direct beneficial effects on hepatic inflammation, thereby improving glucose metabolism in obesity." (PMID 40697664, 2025). "In mouse models of obesity and insulin resistance, EPO administration led to improved glucose tolerance and insulin sensitivity." (PMID 41012526, 2025). "During high-fat diet feeding, EPO treatment increases hematocrit and also exhibits an anti-obesity effect in these female mice, decreasing fat mass accumulation and increasing brown fat-associated gene expression in WAT." (PMID 39996752, 2025). "EPO administration in mice protected against diet-induced obesity, enhanced energy expenditure, and reduced fat accumulation." (PMID 39996752, 2025). "This sex-specific EPO regulation of fat mass is due to the protective effect of estrogen on obesity in female mice that contributes to energy metabolism, insulin sensitivity, and lipid metabolism." (PMID 39996752, 2025). "The association of lower BMI and the level of ESA resistance confirmed in our study can also be observed in the opposite direction since it has been previously shown that EPO can suppress obesity in both pre-clinical and clinical studies." (PMID 39518373, 2024). "Recently, growing attention has been focused on the relation between erythropoietin (EPO) and obesity." (PMID 38696124, 2024). "The obesity-related increased EPO levels are restored after VLCKD intervention at the time of maximum ketosis, suggesting a potential role of the nutritional ketosis induced by the VLCKD." (PMID 38696124, 2024). "Despite these limitations, our study provides new insights into how the EPO–EpoR axis regulates lipid metabolism and improves obesity." (PMID 39284834, 2024). "Abnormal lipid metabolism, particularly in conditions like obesity and metabolic syndrome, can affect EPO efficacy." (PMID 39518373, 2024). "Little or no change in body weight and fat mass was apparent in WT female mice on a high-fat diet treated with EPO due to the protective effect of estrogen against diet-induced obesity mediated via estrogen receptor α." (PMID 38628440, 2024). "For example, the stress alarmone and anorectic protein Gdf15 interact with members of two other groups, including inflammatory Cx3cl1, axon guidance-related protein (Bmp3), and the obesity-related proteins Timp1 and erythropoietin (Epo)." (PMID 39329749, 2024). "This suggests that a factor alternative to EPO is involved in the stimulation of erythropoiesis in obesity, with a prominent candidate being leptin, which is produced by adipose tissue." (PMID 37528422, 2023). "Abnormal efferocytosis in obesity, which is a key factor in type II diabetes, also contributes to defective erythropoietin (EPO) signaling." (PMID 35281078, 2022). "In female mice the protective effect of estrogen against obesity supersedes EPO regulation of fat mass and inflammation, and requires estrogen receptor alpha activity." (PMID 34603036, 2021). "This review focuses on the metabolic activity of EPO such as regulation of fat mass and inflammation during diet induced obesity and sex-dimorphic EPO response in fat and brain." (PMID 34603036, 2021). "Full-heritage Pima Indians exhibit a high prevalence of obesity and type 2 diabetes, and assessment of endogenous plasma EPO level in a subset 79 individuals showed the expected negative association with hemoglobin (p = 0.005)." (PMID 34603036, 2021).
Obesity (continued). "In the liver, EPO inhibited gluconeogenesis, attenuated obesity-related inflammatory cytokine expression and production of TNF-α and IL-6, reduced the activation of NFκB and inflammatory signaling, and enhanced insulin-related PI3K signaling." (PMID 33330462, 2020). "The central finding of our study was that EPO concentration is higher in women with obesity, even when controlling for iron status and inflammation." (PMID 32244712, 2020). "The relationship between EPO and body weight in humans is suggested in a subset analysis of full-heritage Pima Indians with a high prevalence of obesity and type 2 diabetes." (PMID 33330462, 2020). "Few other studies have explored the influence of obesity on EPO concentration; one study in adolescents and another in Mexican adult women, which controlled for inflammation." (PMID 32244712, 2020). "Sex-dimorphic EPO response is related to estrogen in female mice, which interferes with EPO protective activity in fat mass regulation and obesity-related inflammation." (PMID 33330462, 2020). "In the present study, we complement our previous work by evaluating how obesity modifies erythropoietin and red cell indices." (PMID 32244712, 2020). "This sex-dimorphic activity of EPO fat mass regulation is attributed to the anti-obesity effect of estrogen that interferes with EPO regulation of fat mass." (PMID 33330462, 2020). "While elevated EPO improves glucose tolerance in both male and female mice, EPO regulation of fat mass accumulation and inflammation during diet-induced obesity, mediated in part via activity in WAT and the hypothalamus, appears to be sex specific." (PMID 33330462, 2020). "In diet-induced obesity, EPO modulates the proinflammatory response of macrophage infiltration in white adipose tissue and promotes an anti-inflammatory phenotype." (PMID 32038269, 2019). "EPO regulation of pituitary derived ACTH plasma levels suggests a wider role for EPO regulation of metabolism and obesity via the neuroendocrine hypothalamic-pituitary axis." (PMID 32038269, 2019). "We found increased activation of the PI3 K/Akt signaling pathway under hypoxic conditions after rhEPO treatment, and HF diet-inducible-obesity in the EPO Tg and control pigs." (PMID 30834158, 2019). "EPO enhances AKT activation in liver, inhibits gluconeogenesis in high fat diet fed mice and reduces liver inflammation associated with diet induced obesity." (PMID 32038269, 2019). "Here, we provide new evidence that classical brown adipose tissue (BAT) plays an important role in how EPO alleviates obesity and glucose homeostasis in mice." (PMID 28288167, 2017). "Although our dosage was lower than in past investigations, the anti-obesity effects exerted by EPO in our study were consistent with previous studies in animal models." (PMID 28288167, 2017). "We further suggest that BAT is involved in the EPO-mediated anti-obesity effect observed in our study, as BAT increases energy expenditure in organisms by dissipating chemical energy as heat (i.e. thermogenesis)." (PMID 28288167, 2017). "More importantly, exogenous EPO has been deemed to improve obesity and IR, indicating that EPO is a potent regulator of obesity." (PMID 26459940, 2015). "This review discusses these and other reports of EPO action beyond red blood cell production, including EPO response affecting metabolism and obesity in animal models." (PMID 24918289, 2014). "In the present study, we show that over-expression of EPO protects against diet-induced obesity and improves metabolic parameters in obese mice." (PMID 19521513, 2009). "Further support for EPO’s hepatic actions stems from studies outside the context of obesity." (PMID 40697664, 2025).
Obesity (continued). "Other tissues that contribute to EPO activity to improve obesity and glucose homeostasis in obese mice include brown adipose tissue (BAT), in which EPO increased interscapular fat mass, temperature, and secretion of FGF21, a metabolic regulator of glucose homeostasis and insulin sensitivity." (PMID 39996752, 2025). "By increasing EPO levels, ROX may be used in treating obesity caused by high lipid intake, taking into account that the equilibrium between osteogenesis and adipogenesis is managed via EPO/EPOR signaling during the inflammation process caused by obesity." (PMID 41020856, 2025). "Chronic inflammation from obesity causes the liver to release inflammatory factors like TNF-α, IL-1, and IL-6, which upregulate hepatic hepcidin synthesis and may reduce erythropoietin synthesis and activity." (PMID 40709336, 2025). "Together, EPO as a novel regulator of energy homeostasis including lipolytic and lipogenic gene expression provides a potential strategy to enhance metabolic health and protect against obesity." (PMID 39996752, 2025). "EPO treatment improves glucose metabolism in male and female mice and the current study was restricted to male mice because of the overlapping protective effect of estrogen against diet-induced obesity in female mice." (PMID 39284834, 2024). "EPO levels, iron status and body composition parameters were evaluated in 72 patients with overweight or obesity and 27 normal-weight subjects at baseline and after the three different weight-reduction therapies (VLCKD, LCD and BS) in 69 patients with excess body weight." (PMID 38696124, 2024). "EPO metabolic regulation in human is suggested by the negative association between endogenous EPO level and percent weight change per year in male Pima Indians from the Gila River Indian Community with high prevalence of obesity and type 2 diabetes." (PMID 39284834, 2024). "The increased EPO levels observed in obesity could suggest that EPO is secreted to counteract the metabolic deficiencies in these patients with a variable degree of systemic inflammation related with an increase in adipose tissue and cytokine production." (PMID 38696124, 2024). "The increase in EPO concentration could explain the slightly higher mean Hb and RBC in the overweight/obesity group and their positive linear association with all measures of adiposity in this study." (PMID 39236809, 2024). "In addition, EPO attenuates diet-induced obesity, improves glucose tolerance, reduces insulin resistance, and attenuates fat mass accumulation." (PMID 38462569, 2024). "This study aimed to investigate whether the nutritional ketosis and weight loss induced by a VLCKD lead to changes in EPO circulating concentration, compared with a standard, balanced low-calorie diet (LCD) or bariatric surgery in patients with obesity." (PMID 38696124, 2024). "In addition, it also provides new evidence of a potential role of EPO as a marker of the metabolic status related to obesity therapies." (PMID 38696124, 2024). "All eight patients highly suspected of reactive erythrocytosis due to traits such as renal artery stenosis (n = 1), IP and lung cancer (n = 1), COPD (n = 1), chronic heart failure (n = 1), SAS (n = 1), heavy smoking (n = 5), and severe obesity (n = 1) had normal EPO levels." (PMID 35775283, 2023). "EPO also reduced iNOS expression in inflammation during diet induced obesity." (PMID 36895793, 2023). "Literature reports relating EPO to obesity, however, are mainly focused on exogenous EPO administration, which reduces fat accumulation and improves glycaemic characteristics, and little information is available about endogenous EPO in obesity." (PMID 37528422, 2023). "Thus, a possible role of mediator variables, such as obesity, dyslipidemia, and erythropoietin, cannot be excluded." (PMID 36556486, 2022). "Endogenous EPO is protective against obesity induced hypothalamus inflammation." (PMID 34603036, 2021).
Obesity (continued). "Increased circulating EPO by EPO administration in male mice or by over-expression in skeletal muscle via gene electrotransfer in female mice reduced body weight and fat mass during high fat diet induced obesity." (PMID 34603036, 2021). "Unlike EPO regulation of fat mass and inflammation associated with diet-induced obesity, EPO-stimulated bone loss in mice does not appear to exhibit gender bias." (PMID 33330462, 2020). "A sex-dimorphic response of cerebral EPO regulation during diet-induced obesity resulted from estrogen blocking the protective effects of EPO signaling in the brain on fat mass accumulation and hypothalamus inflammation during high-fat-diet feeding in female mice." (PMID 33330462, 2020). "The potential for EPO to regulate fat mass and the increase in EPO production at high altitude may contribute to the lower obesity rate observed in humans residing at a high altitude." (PMID 33330462, 2020). "Evidence suggests that obesity could trigger erythropoietin production and thus stimulate synthesis of Hb." (PMID 31482956, 2019). "This suggests that the activity of EPO to reduce white adipose tissue inflammation in diet induced obesity may contribute to EPO stimulated improvement in insulin resistance." (PMID 32038269, 2019). "The anti-obesity effect of EPO on mice fed high fat diet was restored in ovariectomized mice." (PMID 32038269, 2019). "Further studies of exogenous EPO treatment in mice including genetic mouse models of obesity and transgenic mice constitutively overexpressing human EPO showed that elevated serum EPO levels decreased blood glucose and decreased body weight, especially body weight gain in obese mice." (PMID 32038269, 2019). "The greater increase in fat mass in male mice on high fat diet compared with female mice is evidence of the protective effect of female hormones against diet induced obesity and raises the possibility that female hormones interfere with the anti-obesity effect of EPO observed in male mice." (PMID 32038269, 2019). "Animal studies suggest that EPO may be protective in diet-induced obesity, improves glucose tolerance, reduces insulin resistance and regulates fat mass accumulation, particularly in male mice." (PMID 32038269, 2019). "Thus, EPO’s improvement of obesity and glucose homeostasis can be attributed to increased iBAT thermogenic capacity and activation of BAT’s endocrine functions." (PMID 28288167, 2017). "We investigated whether interscapular brown adipose tissue (iBAT: main part of classical BAT) could play a role in EPO’s anti-obesity and anti-diabetic effects in diet-induced obese mice." (PMID 28288167, 2017). "This study aimed to discover whether EPO acts on classical BAT to exert anti-obesity and anti–diabetic effect in mice fed a high-fat diet." (PMID 28288167, 2017). "In addition, how EPO eminently exerts anti-obesity and anti-diabetic effect only in high-fat diet conditions should be addressed in future studies." (PMID 28288167, 2017). "Furthermore, EPO can lead to wound healing during DM, maintains cellular mitochondrial function and energy metabolism, and reduces the detrimental effects of obesity in animal models." (PMID 26064426, 2015). "Erythropoietin (EPO) has been identified as being crucial for obesity modulation; however, its erythropoietic activity may limit its clinical application." (PMID 26459940, 2015). "Collectively, these data clearly indicated that treatment with EPO after the establishment of obesity-related T2D significantly reduced the body weights, corrected hyperglycemia and glucose intolerance, and mitigated the HFD-induced hyperinsulinemia in HFD-fed mice." (PMID 23326455, 2013). "The main finding is that muscular EPO over-expression protects mice against diet-induced obesity." (PMID 19521513, 2009). "Thus, in recent years, growing attention has been focused on the role of EPO in obesity." (PMID 38696124, 2024).
Obesity (continued). "Thus, the specific role of EPO in the management of human obesity is yet to be elucidated." (PMID 38696124, 2024). "Our results suggest that the EPO–EpoR axis in non-hematopoietic tissue effects may simultaneously alleviate obesity associated metabolic derangements." (PMID 39284834, 2024). "Similarly, male and female nNOS−/− mice on a high-fat diet showed little change in body weight and fat mass with EPO treatment, consistent with the anti-obesity effect of NOS inhibition that may be specific to the loss of nNOS activity." (PMID 38628440, 2024). "Patient-related risk factors included obesity, inherited thrombophilic abnormalities, central venous catheter (CVC), comorbidities (such as infections, cardiac disease, chronic renal disease, immobilization), medications such as erythropoietin and recent surgical procedures (less than 3 months)." (PMID 32899553, 2020). "In addition, the level of EpoR expression in white adipose tissue (WAT), which is secondary to its primary expression site of EpoR in erythroid progenitor cells, suggested the possibility that endogenous EPO action in WAT protects against obesity to maintain energy homeostasis." (PMID 24918289, 2014). "Interestingly, a transgenic animal model of muscular Akt over-expression showed a similar phenotype as our EPO expressing mice with muscle fibre hypertrophy, resistance to diet-induced obesity and significant improvements in several metabolic variables including glucose tolerance." (PMID 19521513, 2009). "Conversely, when mice were injected with EPO and RUNX1 inhibitors, they exhibited glucose intolerance and insulin resistance, and developed obesity." (PMID 39996752, 2025). "These three studies are highlighted here as they provide valuable insights into the relationship between EPO and WAT inflammation in obesity, representing the most informative data currently available." (PMID 40697664, 2025). "Improvement in blood pressure, lipids, hemoglobin targets on erythropoietin in CKD IV-V, and lesser smoking and obesity were achieved." (PMID 36240220, 2022). "Our study included patients with myeloma who had a different risk of VTE, because of the presence of individual factors, such as obesity, recent surgery, presence of comorbidities, a history of VTE or treatment with erythropoietin." (PMID 32899553, 2020). "The fact that higher concentrations of EPO were observed in the obesity group may suggest a physiological compensatory mechanism for ensuring adequate erythropoiesis in cases with low available iron, such as pregnant women with obesity or those in need of iron supplementation." (PMID 32244712, 2020). "In conclusion, EPO inhibits BMAT in RCD-fed mice and prevents excessive BMAT accumulation in diet-induced obesity, thus preventing the conversion to fatty marrow." (PMID 32121294, 2020). "In adipocytes, EPO has been found to decrease preadipocyte differentiation, and mice with adipocyte-specific deletion of EPOR exhibited obesity and decreased glucose tolerance and insulin sensitivity." (PMID 26459940, 2015). "Robust evidence from animal and cellular studies supports the anti-inflammatory and metabolic effects of EPO; however, clinical data on non-hematopoietic EPO analogs in patients with obesity and metabolic disorders remain limited." (PMID 40697664, 2025). "Although evidence in obesity-related inflammation remains limited, these findings support the therapeutic potential of non-hematopoietic EPO analogs." (PMID 40697664, 2025). "The non-erythroid EPOR agonist ARA290 also improves diet-induced obesity and glucose tolerance providing evidence for EPO regulation of fat metabolism independent of EPO stimulated erythropoiesis." (PMID 39996752, 2025). "Knock out of the EPO receptor in non-hematopoietic tissues in animal models results in increased fat mass without affecting lean mass and treatment of mice with EPO, or forced EPO overexpression, protects against obesity and improves glucose tolerance." (PMID 37029208, 2023).